OXTR (oxytocin receptor)
Diseases named in the same sentence as OXTR in open-access papers (continued):
Sharing a sentence is not in itself a finding about the gene and the disease.
autism (continued). "The findings of the current study suggest that the OXTR can explain some of the within-group variability in self-other differentiation, which is not otherwise captured by comparing individuals with and without autism." (PMID 30918622, 2019). "While the increase of OXTR in the autism brain samples may not be intuitive, this finding validates a previous study of increased OXTR expression in the frontal cortex of autistic individuals." (PMID 26273428, 2015). "In addition one study of a Caucasian sample found no influence of various SNPs of the OXTR gene on autism, although they did not include the rs2254398." (PMID 26599592, 2015). "Our family analysis identified an OXTR deletion in the mother who does not present with autism." (PMID 19845972, 2009). "Although, the results of these early studies indicate that if OXTR dysfunction plays a role in both autism and depression, its contribution is not specific to any of these diseases but might rather facilitate disturbances in the brain functions related generally to mental disorders." (PMID 36835321, 2023).
depression (74 papers, 2011 to 2025). "For instance, methylation of the OXTR gene, which encodes the oxytocin receptor, has been linked to emotional regulation and social functioning in depression." (PMID 41303496, 2025). "Polymorphisms within OXTR, including SNP rs53576, have been shown to be associated with depression, maternal sensitivity, and also aspects of breastfeeding such as occurrence of nipple pain." (PMID 41470006, 2025). "One genetic association study identified a link between oxytocin receptor gene polymorphisms and depression." (PMID 40076753, 2025). "For these reasons, alterations in the methylation of OXTR have been associated with autistic spectrum disorders, callous–unemotional traits, and depression." (PMID 40867587, 2025). "This suggests that lower methylation at CpG sites is associated with higher transcriptional activity of the OXTR gene, potentially leading to increased oxytocin receptor expression in the brain areas implicated in depression." (PMID 38792892, 2024). "Taking into account previous findings, we suggest that the OXTR gene rs53576 polymorphism is an indispensable moderating variable in relation to the linkage between poor peer association, depression, and NSSI in adolescents." (PMID 39767874, 2024). "Although no empirical studies have directly investigated the regulatory function of the OXTR gene rs53576 polymorphism in the correlation between depression and NSSI, some findings provide indirect evidence." (PMID 39767874, 2024). "The OXTR gene rs53576 polymorphism will moderate the effects of deviant peer affiliation on adolescent depression and NSSI." (PMID 39767874, 2024). "The OXTR gene rs53576 polymorphism moderates the relationship between depression and adolescent NSSI." (PMID 39767874, 2024). "As in the case of autism spectrum disorder, studies on the role of OXTR in depression started from analyses of the OXTR gene polymorphisms in patients with the latter disease." (PMID 36835321, 2023). "Depression and self-esteem are genetically related, mainly by the oxytocin receptor gene, which is linked to the domains of self-esteem, optimism, and depression." (PMID 36625979, 2023). "As evidenced above, the published conclusions on the role of OXTR polymorphism and methylation in depression are contradictory, making the question unanswered." (PMID 36835321, 2023). "These discrepancies did not solve the problem, but rather deepened the confusion and ambiguity about the putative role of the OXTR polymorphism in depression." (PMID 36835321, 2023). "Two polymorphic variations of oxytocin receptor (OXTR) rs2254298 and rs53576 located at intron 3 were associated with depression." (PMID 35207633, 2022). "Hierarchical multiple regression analysis showed that paternal rejection was related to self-reported depression and that the effect of parental rejection was moderated by OXTR gene polymorphisms and nationality." (PMID 35564961, 2022). "The aim of the current study was to investigate a possible association between the methylation status of the OXTR gene promoter region and severity of depression symptoms as well as early life adversities." (PMID 35672748, 2022). "Secondly, while associations were found between parental rejection, OXTR SNP genotype and ethnicity in depression, the mechanisms mediating this relationship have yet to be elucidated." (PMID 35564961, 2022). "The results suggest that the GG genotype carriers were less responsive to environmental contingencies, based on Brüne’s suggestion that the A allele of OXTR rs2254298 is a relatively recently evolved allele that often plays a role in depression." (PMID 35222513, 2021). "Studies suggest that children of mothers with depression during the pregnancy have higher circulating cortisol with associated alterations in the oxytocin receptor (OXTR) function." (PMID 34639416, 2021).
depression (continued). "More specifically, hypomethylation of CpGs located in the promoter region of OXTR exon 1 and hypermethylation of sites located in OXTR intron 3 have been associated with depression and anxiety disorders in subjects with a history of childhood abuse." (PMID 34073101, 2021). "Carriers of the G allele of the OXTR rs53576 gene are more likely to have co-morbid PTSD-depression." (PMID 35046844, 2021). "One small candidate gene study did report evidence for involvement of OXTR gene single nucleotide polymorphisms (SNPs) rs2254298 and rs53576 in clinically diagnosed major depressive disorder." (PMID 28353027, 2017). "The null findings regarding associations between OXTR SNPs and depression are in line with recent GWA studies." (PMID 28353027, 2017). "Only a small candidate gene study by the Costa and colleagues has so far shown associations between OXTR SNPs and clinical diagnoses of depression." (PMID 28353027, 2017). "More recent findings show that another OXTR SNP (rs53576) moderated the association between maternal depression in early childhood and depressive symptoms in a sample of 441 adolescents." (PMID 28353027, 2017). "Girls who were heterozygous (A/G) for the OXTR rs2254298 polymorphism and reported high levels of adversity exhibited the most severe depression as well as physical symptoms and social anxiety." (PMID 24596569, 2014). "Another OXTR polymorphism, rs53576, has previously been shown to associate with maternal sensitivity and depression." (PMID 23637833, 2013). "To conclude, we present a novel investigation of associations between maternal lifetime history of depression, maternal prenatal DNA methylation at the OXTR gene, which is linked to breastfeeding and known to be epigenetically regulated under conditions of stress, and breastfeeding outcomes." (PMID 41470006, 2025). "Additionally, previous research has demonstrated that mothers with depression have elevated DNA methylation at OXTR, which is associated with reduced oxytocin signalling." (PMID 41470006, 2025). "We further investigated whether the OXTR gene rs53576 polymorphism conditioned the indirect connection, through depression, between deviant peer affiliation and adolescent NSSI." (PMID 39767874, 2024). "Methylation of the Oxtr (oxytocin receptor) gene might play an important role in ELS-induced susceptibility to depression in adult mice." (PMID 39457754, 2024). "The OXTR gene rs53576 polymorphism may operate as a modulator of how adolescent depression affects their NSSI." (PMID 39767874, 2024). "Thus, it is our conjecture that the OXTR rs53576 gene polymorphism will exert an influence on the relationship linking adolescent NSSI to depression." (PMID 39767874, 2024). "Such a hypothesis can be supported by the results of studies on chronic stress, which is both the major risk factor for depression and significantly influences OXTR expression." (PMID 36835321, 2023). "The rs53576 has been further correlated with depression, as it was reported that this OXTR polymorphism, particularly the ‘A’ allele, may be partially responsible for the transmission of maternal depression to youth." (PMID 36835321, 2023). "Longitudinal studies, as well as the replication of this study with clinical population samples (i.e., individuals clinically diagnosed with depression), would provide a clearer picture of the association between parental rejection and OXTR genotypes in depression during development." (PMID 35564961, 2022). "Transferred to the results of our study, one may expect increased oxytocin receptor expression in brain areas that are implicated in depression." (PMID 34822109, 2022). "In terms of human research on the link between OXTR and psychopathology, both family and population studies have linked several OXTR single-nucleotide polymorphisms (SNPs)—variants in alleles at a particular gene locus—with psychopathology involving social dysfunction, including depression." (PMID 35564961, 2022).
depression (continued). "It remains to be shown whether depression is also associated with a higher expression rate of the oxytocin receptor." (PMID 34822109, 2022). "In particular, we expect that OXTR polymorphisms may moderate the association between perceived parental rejection and the level of depression." (PMID 35564961, 2022). "Using human blood samples, studies have associated OXTR CpG island methylation with child conduct disorder, obsessive-compulsive disorder, social behaviors, anxiety disorders, depression, and autism spectrum disorder." (PMID 34178979, 2021). "Both OXTR SNPs were also hypothesized to be associated with unipolar depression and with risk for autism spectrum disorder." (PMID 23284802, 2012). "It is therefore reasonable to hypothesize that depression prior to birth could result in the alteration of DNA methylation at genes which are important for breastfeeding, such as OXTR, which in turn is associated with poor milk ejection and reduced milk volume." (PMID 38834917, 2025). "In line with hypothesis 3, we found that the OXTR gene rs53576 polymorphism moderated the connection between depression and adolescent NSSI, given that the moderating impact of the rs53576 polymorphism was mostly evident in the regulation of negative emotions (depression) caused by deviant peers." (PMID 39767874, 2024). "The three-way interaction between paternal rejection, OXTR gene polymorphism and ethnicity significantly predicted depression, where the rs53576 genotype and ethnicity moderated the association between paternal rejection and depression, R2diff = 0.037, p = 0.046." (PMID 35564961, 2022). "Given that adverse early life experiences and stress, such as abuse and neglect, in combination with OXTR genotypes, are associated with an increased risk of depression, these findings further strengthen the argument for oxytocin as a candidate gene related to depression." (PMID 35564961, 2022). "Secondly, the A allele of OXTR rs2254298 has been suggested to be involved in plasticity processes, which increases resilience in dealing with stressful environments, especially those occurring during early life that often play a role in susceptibility to depression in individuals." (PMID 35564961, 2022). "The three-way interaction between maternal rejection, OXTR gene polymorphism and ethnicity significantly predicted depression, where ethnicity moderated the interaction effect between maternal rejection and rs2254298 genotype on predicting depression, R2diff = 0.041, p = 0.018." (PMID 35564961, 2022). "Moreover, besides OCD, OXTR DNA methylation at exon 3 has been associated with other central nervous system disorders such as anxiety disorder, autism spectrum disorder, depression and psychopathy." (PMID 35361281, 2022). "The three-way interaction between paternal rejection, OXTR gene polymorphism and ethnicity significantly predicted depression, where ethnicity moderated the interaction of paternal rejection and rs2254298 genotype in predicting depression, R2diff = 0.037, p = 0.013." (PMID 35564961, 2022). "In the context of DNAm, higher methylation of the OXTR gene was associated with depression and early life adversity, suggesting that DNAm of the OXTR might contribute to the pathophysiological transition from chronic stress (i.e., CM) to stress-related pathology." (PMID 34471100, 2021). "This study examined associations between lifetime history of depression (LHD), prenatal oxytocin receptor gene (OXTR) DNA methylation, and breastfeeding outcomes." (PMID 41470006, 2025). "Depression-like behavior following viral knockdown of OXTR expression in nucleus accumbens also suggests a potential role of this brain region in expression of other indices of pair bonding." (PMID 38798348, 2024). "Support for such a proposal arises also from the results of studies in which correlations between the OXTR genotype and anxiety, stress, and depression scores were depicted." (PMID 36835321, 2023).
depression (continued). "On the other hand, when OXTR methylation and rs53576 were investigated in another study, a greater DNA methylation was observed in patients with depression, but only in the presence of the AA genotype at rs53576." (PMID 36835321, 2023). "Firstly, for rs53576, a significant gene–environment interaction effect was found between paternal rejection and OXTR SNP genotype on depression but only in the Japanese sample." (PMID 35564961, 2022). "The present study aimed to investigate gene–environment interaction effects between parental rejection and OXTR SNP genotypes of rs53576 and rs2254298 on self-reported depression in adults in different cultural contexts." (PMID 35564961, 2022). "Secondly, for rs2254298, a significant gene–environment interaction effect was found between both paternal and maternal rejection and OXTR SNP genotypes on depression but only in the Italian sample." (PMID 35564961, 2022). "In a post-mortem study of persons suffering from major depression, the expression of mRNA for the oxytocin receptor was significantly increased in the dorsolateral prefrontal cortex." (PMID 34822109, 2022). "In the current paper, four types of 5-HT heteroreceptor complexes (5-HT1AR-FGFR1, 5-HT1A-5-HT2AR, OXTR-5-HT2A/C) have been selected to give insights into this novel field with a focus on their relevance for depression." (PMID 33672070, 2021). "Increased expression of OXTR was reported in the prefrontal cortex of patients with depression and bipolar disorder." (PMID 33516250, 2021). "Studies on NR3C1, OXTR, and other candidate genes reported mixed findings in terms of methylation modification and depression." (PMID 30718449, 2019). "The results revealed a significant effect in the interaction between OXTR rs53576 genotype and maternal postpartum depression on externalising problems in children with AA genotype (β = 0.136, 95% CI 0.032 to 0.240), but not in those with GG/GA genotype." (PMID 31118457, 2019). "Herein, an attempt was made to investigate the interaction effect of OXTR rs53576 genotype × maternal depression on child behavioural problems, using a representative sample of the general population in Japan." (PMID 31118457, 2019). "Unadjusted and adjusteda odds ratios and 95% confidence intervals for postpartum depression by OXTR rs53576 genotype and OXTR methylation site -934, stratified by presence or absence of depression in pregnancy." (PMID 26257770, 2015). "These preliminary results suggest that genetic (SNV) and epigenetic (DNA methylation) factors interactions in BDNF and eventually in OXTR genes are involved in the anxiety disorders/depression phenotype in older adults." (PMID 26175754, 2015). "In the present study, we examined the association between genetic/epigenetic variation in the OXTR gene (measured in blood during pregnancy) and PPD (defined as elevated symptoms of depression 8 weeks after birth)." (PMID 26257770, 2015). "We reported that OXTR interacted with a family stressor, parental divorce, during adolescence, to predict depression in young adulthood (differentially for males and females)." (PMID 26441708, 2015). "One study reported an interaction of OXTR rs2254298 and adverse parental environment in predicting symptoms of depression in 9–14 years old girls." (PMID 24596569, 2014). "Other studies report associations of another OXTR polymorphism, rs53576, on several intermediate phenotypes that are relevant in the link between ELS and depression, which are reviewed below." (PMID 24596569, 2014). "The moderating role of OXTR genotype on the relation between childhood maltreatment and depression was significant, Δ R2 = 0.02, b = −2.47, t = −2.42, p = 0.02." (PMID 23898235, 2013). "Among the many factors that moderate and/or mediate the relationship between early adversity and adult depression are the timing of the early adversity, the presence of social support during development, oxytocin function and OXTR genotypes." (PMID 23637833, 2013).